STRA6 (signaling receptor and transporter of retinol STRA6)
Description:
Functions as a retinol transporter. Accepts all-trans retinol from the extracellular retinol-binding protein RBP4, facilitates retinol transport across the cell membrane, and then transfers retinol to the cytoplasmic retinol-binding protein RBP1. Retinol uptake is enhanced by LRAT, an enzyme that converts retinol to all-trans retinyl esters, the storage forms of vitamin A. Contributes to the activation of a signaling cascade that depends on retinol transport and LRAT-dependent generation of retinol metabolites that then trigger activation of JAK2 and its target STAT5, and ultimately increase the expression of SOCS3 and inhibit cellular responses to insulin. Important for the homeostasis of vitamin A and its derivatives, such as retinoic acid. STRA6-mediated transport is particularly important in the eye, and under conditions of dietary vitamin A deficiency (Probable). Does not transport retinoic acid.
Synonyms: PP14296; SLC69A1; FLJ12541; MCOPCB8; MCOPS9
Tractability: Antibody: UniProt places it where antibodies can reach, with high confidence; its Gene Ontology location is reachable by antibodies, with high confidence; UniProt predicts a signal peptide or a membrane-spanning region. PROTAC: ubiquitination databases record sites on it.
Gene: Protein-coding gene on chromosome 15 (74,179,466 to 74,212,267, reverse strand). Ensembl gene ENSG00000137868.
Subcellular location: Cell membrane
Pathways (Reactome):
Disease: Defective visual phototransduction due to STRA6 loss of function
Sensory Perception: The canonical retinoid cycle in rods (twilight vision)
Gene Ontology:
Molecular function: retinol transmembrane transporter activity; signaling receptor activity
Biological process: adrenal gland development; alveolar primary septum development; artery morphogenesis; blood vessel development; camera-type eye development; cognition; developmental growth; diaphragm development; digestive tract morphogenesis; ductus arteriosus closure; ear development; embryonic camera-type eye formation; embryonic digestive tract development; eyelid development in camera-type eye; face morphogenesis; feeding behavior; female genitalia development; head development; head morphogenesis; heart development; kidney development; learning; lung alveolus development; lung development; lung vasculature development; and 12 more
Cellular component: plasma membrane; protein-containing complex
Genetic constraint (gnomAD): Loss-of-function variants: 48 observed, 84.16 expected, observed/expected ratio (o/e) 0.57, 90% interval 0.45 to 0.73. The upper end of that interval is the gene's LOEUF score, 0.73, which puts it in group 2 of 6, group 1 being the genes least tolerant of losing a copy. Missense variants: 756 observed, 845.89 expected, observed/expected ratio (o/e) 0.89, 90% interval 0.84 to 0.95. Synonymous variants: 350 observed, 368.84 expected, observed/expected ratio (o/e) 0.95, 90% interval 0.87 to 1.04.
Homologues: Orthologues: chimpanzee STRA6 (99% identical), macaque STRA6 (96% identical), pig STRA6 (83% identical), dog STRA6 (78% identical), mouse Stra6 (74% identical), rat Stra6 (74% identical), rabbit STRA6 (73% identical), guinea pig STRA6 (71% identical), zebrafish stra6 (41% identical), tropical clawed frog stra6 (40% identical). Paralogues in human: CCDC180 (15% identical).
Diseases named in the same sentence as STRA6 in open-access papers:
STRA6 is named in the same sentence as 90 diseases in open-access papers, as found by Europe PMC text mining. Sharing a sentence is not in itself a finding about the gene and the disease. The quoted sentences say what the papers report.
microphthalmia (19 papers, 2008 to 2025). Congenital or developmental anomaly in which the eyeballs are abnormally small. "Stra6 is expressed in cardiac tissue and Stra6 mutations are associated with congenital defects, including microphthalmia/anophthalmia and cardiac malformations (Matthew-Wood syndrome)." (PMID 41035698, 2025). "In F1, the proband (III-1) had microphthalmia and osteogenesis imperfecta, with variants in STRA6 and SERPINF1 respectively." (PMID 34276053, 2021). "STRA6 mutations during development can lead to anophthalmia, microphthalmia, and other symptoms that overlap with phenotypes associated with Matthew-Wood syndrome." (PMID 34836244, 2021). "Recent reports indicate that single nucleotide polymorphisms or mutations in STRA6 gene are correlated with the congenital eye malformations microphthalmia, anophthalmia and coloboma as well as Matthew-Wood syndrome." (PMID 24391722, 2013). "Homozygous mutations in STRA6 result in a multiple malformation syndrome typically associated with anophthalmia or microphthalmia, the latter also observed in one patient with 15q24 deletion syndrome." (PMID 20678247, 2010). "STRA6 expression is predominant in cells with high vitamin A requirements, such as the retinal pigmented epithelium in the eye, which explains why mutations in STRA6 typically result in microphthalmia and other congenital defects." (PMID 39624361, 2024). "Remarkably, mutations in the STRA6 gene are seen in ocular defects in humans, such as coloboma and microphthalmia, and our patient presented eye coloboma, suggesting a potential and specific contribution of the hypo-methylation to the eye phenotype of the patient." (PMID 33530447, 2021). "Haploinsufficiency of STRA6 may cause a group of congenital malformations, including microphthalmia, cardiovascular malformations, diaphragmatic hernia, and mental retardation." (PMID 34922566, 2021). "Another missense variation T > C P. Y374C of STRA6 gene was identified in patient with microphthalmos." (PMID 32962661, 2020). "Single-gene deletions and mutations affecting the ability to produce proteins and enzymes such as SOX2, MFRP, ALDH1A3, STRA6, PAX2, and OTX2, have been identified as causing isolated microphthalmia and anophthalmia and syndromic forms." (PMID 30153864, 2018). "The most plausible developmental link is disruption of the retinoic acid signaling pathway, where mutations in STRA6 and RARB give rise to the PDAC/Matthew–Wood syndrome, characterized by microphthalmia, pulmonary hypoplasia/agenesis, and diaphragmatic defects." (PMID 40941759, 2025). "Analysis revealed one missense alteration G12411T of Zinc Finger Homeobox 4 (ZFHX4) gene in one participant among 10 with congenital ptosis and another missense variation T > C P. Y374 C of Signaling Receptor and Transporter Retinol 6 (STRA6) gene in one participant among 3 with microphthalmos." (PMID 32962661, 2020). "Absence of Stra6 in zebrafish impairs retinoic acid receptor signalling and gene regulation, resulting in craniofacial and cardiac developmental defects, as well as microphthalmia." (PMID 31416264, 2019).
Anophthalmia (16 papers, 2008 to 2025). Absence of the globe or eyeball. "STRA6 mutations cause a wide spectrum of pathological phenotypes including anophthalmia, mental retardation, congenital heart defects, lung hyperplasia, intrauterine growth retardation, and embryonic lethality." (PMID 26343735, 2015). "More recently bi-allelic mutations in STRA6 have emerged as a rare but important cause of isolated anophthalmia in addition to the often lethal syndromal form." (PMID 24498598, 2013). "However, milder phenotypes have been observed, including a patient with bilateral anophthalmia and mild syndromic features, in addition to isolated AM in patients with homozygous missense STRA6 variants." (PMID 31416264, 2019). "Sequencing of the STRA6 (Stimulated-by-retinoic acid-6; Accession number NM_022369) gene that is mutated in individuals with a phenotype comprising anophthalmia, diaphragmatic defects, cardiac malformations and pulmonary agenesis, was performed on the propositus, and was negative." (PMID 20485507, 2010). "The phenotype in humans with a STRA6 mutation includes OFT anomalies, whereas extracardiac anomalies highly resemble the phenotype of the Lrp2 knockout mouse, and humans with an LRP2 mutation with diaphragmatic hernia and anophthalmia." (PMID 26822476, 2016). "Although human STRA6 mutations can cause anophthalmia, human RBP mutations were previously not known to cause anophthalmia." (PMID 26343735, 2015).
colon carcinoma (10 papers, 2014 to 2024). "Downregulating STRA6 or RBP4 in colon cancer cells reduces the proliferation of cancer stem cells and sphere formation." (PMID 38913193, 2024). "In a xenograft mouse model of colon cancer, STRA6 activation triggers a JAK2-STAT3 signaling cascade, promoting tumorigenesis." (PMID 38913193, 2024). "A subsequent study showed that down-regulation of STRA6 in colon cancer cells decreased the fraction of cancer stem cells." (PMID 32012980, 2020). "STAT3 is a known driver of oncogenesis and indeed, activation of STRA6 signaling was demonstrated to promote tumor progression in a STAT3-dependent manner using a xenograft model of colon cancer." (PMID 28689994, 2017). "Downregulating STRA6 or RBP4 in colon cancer cells decreased the fraction of cancer stem cells and their sphere and tumor initiation frequency." (PMID 28689994, 2017). "Previously, STRA6 was overexpressed in breast and colon tumor tissue compared with healthy tissue; however, it is unknown the expression or variation within lung cancer." (PMID 33324556, 2020). "Knockdown of STRA6 or RBP4 in SW480 colon carcinoma cells decreased the levels of NANOG and SOX2." (PMID 28689994, 2017). "Downregulating STRA6 or RBP4 in colon cancer cells decreases CSC population and self-renewal." (PMID 28689994, 2017). "Together, these data demonstrate a key role of STRA6 and RBP4 in the maintenance of colon cancer self-renewal and that this pathway is an important link through which consumption of HFD contributes to colon carcinogenesis." (PMID 28689994, 2017). "To examine the effect of STRA6 and RBP4 on colon cancer growth we generated, using lentiviral short hairpin RNA (shRNA), SW480 colon adenocarcinoma cell lines in which STRA6 or RBP4 were stably downregulated." (PMID 28689994, 2017). "STRA6 activation transduces a JAK2-STAT3 signaling cascade and promotes tumorigenesis in a xenograft mouse model of colon cancer." (PMID 28689994, 2017). "They demonstrated that transfection with STRA6 induced a substantial amount of apoptosis in RA sensitive ovarian cancer cells (specifically PA-1 and A1847) as well as in RA insensitive HCT116 colon cancer cells." (PMID 25340777, 2014). "For MCF-7 breast cancer cells and colon cancer cells, increased expression of the Stra6 protein had impaired all-trans-retinol uptake and Stra6 was not detectable in healthy colon tissue." (PMID 38928275, 2024).
Matthew-Wood syndrome (10 papers, 2008 to 2025). Matthew-Wood syndrome is a rare clinical entity including as main characteristics anophthalmia or severe microphthalmia, and pulmonary hypoplasia or aplasia. "STRA6 mutations cause Matthew-Wood syndrome, which is characterized by malformations, including congenital heart defects." (PMID 41035698, 2025). "In a research sample of fetuses with Matthew-Wood Syndrome, a range of STRA6 insertion and deletion mutations were found in transcripts." (PMID 38673863, 2024). "Mutations in human STRA6 are associated with Matthew-Wood syndrome, which is characterized by severe developmental defects." (PMID 25816144, 2015). "Mutations in human STRA6 can cause Matthew-Wood syndrome, which is characterized by variable combinations of severe developmental defects such as microphthalmia/anophthalmia, cardiac abnormalities, pulmonary dysplasia and diaphragmatic hernia." (PMID 25816144, 2015). "Commonly, pathogenic recessive STRA6 variants result in Microphthalmia, Syndromic 9 (MCOPS9), also known as Matthew Wood Syndrome, where syndromic features include pulmonary, diaphragmatic and cardiac defects, resulting in death within the first 2 years of life." (PMID 31416264, 2019). "The von Lintig lab generated a novel STRA6 knockout mouse model to further establish the role of STRA6 in maintaining vitamin A homeostasis in ocular development and function, as well as gain a greater understanding of how STRA6 related diseases such as Matthew-Woods Syndrome are caused and treated." (PMID 34836244, 2021). "One such disease involving dysfunction on STRA6 is Matthew-Wood Syndrome, a disease characterized by a spectrum of congenital ocular deformations such as microphthalmia, congenital organ malformations, and mental developmental deficiencies." (PMID 38673863, 2024). "Recently, homozygous mutations in the stimulated by retinoic acid gene 6 (MCOPS9; STRA6) were identified in families with Matthew-Wood syndrome, an A/M phenotype associated with pulmonary hypoplasia and cardiovascular malformations." (PMID 19112531, 2008). "Given the adverse contribution of RBP4 to the response of ischemic injury in mice and the phenotype observed in patients with Matthew-Wood syndrome, RBP4 rather than STRA6 might be a potential therapeutic approach for the treatment of MI." (PMID 41035698, 2025).
Insulin resistance (9 papers, 2010 to 2024). Increased resistance towards insulin, that is, diminished effectiveness of insulin in reducing blood glucose levels. "Consistently, adipocytes exposed to glucolipotoxicity and VAT tissue of HFD-fed insulin-resistant rats exhibit significantly increased RABP4/STRA6 expression that mediates AT inflammation and insulin resistance." (PMID 35406450, 2022). "Whether STRA6, which binds to RBP at nanomolar affinity, is involved in sensing RPB to cause insulin resistance has been discussed in detail previously and is only briefly discussed here." (PMID 26343735, 2015). "Recent research indicates, indeed, that STRA6 is not only responsible for ROH intake but also, through the binding of RBP4 and ROH, can be involved in the onset of insulin resistance through the activation of the JAK/STAT pathway." (PMID 34945773, 2021). "As a cell surface receptor of RBP4, STRA6 activated JAK2-STAT5 signal pathway, induced production of SOCS-3 by combining with retinol-RBP4 complexes, and led to insulin resistance to promote the occurrence of T2DM." (PMID 27446956, 2016). "In fact, RBP4 has been shown to play a role in TLR4-mediated inflammatory signaling and insulin resistance independent of STRA6." (PMID 28689994, 2017). "They claimed that the STRA6 binds only holo-RBP, not apo-RBP, and that holo-RBP’s binding to STRA6 causes insulin resistance." (PMID 26343735, 2015). "Fifth, independent studies by Farjo and colleagues and Norseen and colleagues showed that RBP’s effect on insulin resistance is independent of STRA6." (PMID 26343735, 2015). "The deletion of Stra6 in mice reduces insulin resistance mediated by the injection of holo-RBP and feeding of a high-fat diet, suggesting that STRA6 functions as a receptor to mediate RBP-induced insulin resistance." (PMID 26237385, 2014). "However, the role played by STRA6 in pregnancies complicated by insulin resistance has not been explored yet, and uncertainty remains regarding the underlying mechanisms potentially involved." (PMID 34945773, 2021). "The triad of GLUT4-RBP4-STRA6 may play an important role in the pathogenesis of type 2 diabetes, wherein the adipocyte specific down regulation of GLUT4 leads to an increased expression of RBP4 and this increase in RBP4 expression leads to insulin resistance via STRA6." (PMID 20625434, 2010). "But neither functional nor genetic studies have been carried out to identify how STRA6 may play a role in imparting the effect of RBP4 on muscle and liver insulin resistance and subsequently type 2 diabetes." (PMID 20625434, 2010).
vitamin A deficiency (7 papers, 2012 to 2025). Deficiency of vitamin A due to malnutrition, malabsorption, or dietary lack. "Cumulative distribution analysis showed decreased expression of cytoskeleton and ECM-receptor interaction genes in Sham-operated groups following Stra6 deletion and vitamin A deficiency, which was reversed by the combination of both." (PMID 41035698, 2025). "MI was induced in mice with Stra6 germline deletion, vitamin A deficiency (VitAD) by combined lecithin-retinol acyltransferase (Lrat) germline deletion and feeding with a vitamin A-deficient diet." (PMID 41035698, 2025). "The significance of STRA6 in the intrinsic pathway for ocular vitamin A homeostasis has been highlighted under conditions of vitamin A deficiency, as circulating holo-RBP is the sole mode of transport on such restricted diets." (PMID 35452666, 2022). "The association between diabetes and vitamin A deficiency is further corroborated by our studies in Stra6-/- mice." (PMID 35740038, 2022). "Here, we compared the effects of streptozotocin-induced diabetes in wild-type (WT) mice and Stra6-/- mice, a mouse model for ocular vitamin A deficiency." (PMID 35740038, 2022). "Complementary to this, genetic studies from the von Lintig group using Stra6 KO animals, showed that loss of STRA6 leads to vitamin A deficiency in the eyes, manifesting in severe retinal phenotypes." (PMID 32365517, 2020). "Stra6-/- mice display ocular vitamin A deficiency and unliganded opsin even on vitamin A rich diets, thus allowing us to study the interaction of diabetes and vitamin A deficiency in the eyes of these mice." (PMID 35740038, 2022). "Therefore, we compared the short-term and long-term consequences of diabetes in wild-type (WT) mice and Stra6-/- mice, a model for ocular vitamin A deficiency." (PMID 35740038, 2022). "Regarding the use of aerosolized retinoic acid, the authors suggested that STRA6 function was lost due to a blockade by the COVID-19 spike protein, which binds to it with high affinity, hijacking the signaling pathway, leading to disruption of retinoic acid synthesis and vitamin A deficiency." (PMID 37366867, 2023). "Despite the growing dependence of other organs on vitamin A in evolution, the eye is still the organ most dependent on vitamin A. For human, the eye is the organ most sensitive to vitamin A deficiency, the loss of RBP, or the loss of STRA6." (PMID 23363998, 2012). "In both mice and humans, the eye is the organ most sensitive to vitamin A deficiency, loss of RBP, or loss of STRA6." (PMID 23363998, 2012). "Stra6-/- mice displayed ocular vitamin A deficiency on diets with preformed vitamin A, and there was no significant improvement of this condition in mice fed copious BC." (PMID 35452666, 2022).
coloboma (6 papers, 2013 to 2025). An abnormality in which a part of a structure in one or both eyes is missing. "Cross-sectional SD-OCT imaging revealed additional structural defects in albino Stra6−/− mice beyond the coloboma regions." (PMID 41135684, 2025). "Areas of non-perfusion were also detected in Stra6−/− mice irrespective of diet, likely reflecting colobomas characteristic of this genotype, but were absent in control mice." (PMID 41135684, 2025).